MICA (MHC class I polypeptide-related sequence A)
Diseases named in the same sentence as MICA in open-access papers (continued):
Sharing a sentence is not in itself a finding about the gene and the disease.
tumor (continued). "However, it has been demonstrated that MICA shedding from tumor cell surface occurs in a variety of malignant epithelial tumors, including advanced hepatocellular carcinoma, colon, prostate, renal, and breast cancer, as well as hematopoietic tumors." (PMID 18208618, 2008). "Additionally, dual-targeting CAR-NK cells against PD-L1 and MICA/B in lung cancer showed superior cytotoxicity by addressing tumor heterogeneity, while in nasopharyngeal carcinoma, combining CAR-NK cells with nivolumab enhanced NK and CD8+ T cell activity, resulting in synergistic tumor suppression." (PMID 40536609, 2025). "Furthermore, pharmacologic inhibition of MICA/B shedding enhances antitumor immunity and controls tumor growth in animal models, suggesting that inhibition of shed NKG2DLs may be a promising mechanism to reinvigorate antitumor immunity." (PMID 40116579, 2025). "Therefore, MICA-129 polymorphism is not an alternative to PD-L1 checkpoint inhibition in terms of tumor mutation burden." (PMID 41431073, 2025). "However, after binding, they cannot activate the downstream signaling pathway of NKG2D, and they cannot activate NK cells to exert the effect of killing tumor cells; these soluble ligands occupy the binding domain of NKG2D and MICA/B, which are expressed on tumor cells." (PMID 40563539, 2025). "MICA and MICB (MHC-class I-associated chain A/B) serve as ligands for NKG2D, which activates the NK cell cytotoxic function by binding to the NKG2D receptors on NK cell surfaces, thus enabling the recognition and destruction of tumor cells that produce these molecules." (PMID 40066091, 2025). "Beside tumor cells, MICA/B could be expressed on immune cells in the TME." (PMID 38882209, 2024). "MICA exhibits a very low tumor mutation burden, suggesting that its expression is not significantly affected by DNA editing mechanisms, so NKG2DL overexpression may be a potent strategy for anti-tumor progression." (PMID 39906665, 2024). "Additionally, we observed a significant upregulation of MICA in tumor cells." (PMID 38254761, 2024). "Finally, the recent innovative CAR‐NK/NKG2D CAR‐T and MICA/B vaccines in tumor were summarized." (PMID 38882209, 2024). "However, it should be taken into consideration that blocking antibodies that generated by BLS‐MICA may impair the recognition of MICA/B expressing tumors by NK cell and reducing the tumor surveillance." (PMID 38882209, 2024). "Moreover, Badrinath, Set al. developed a vaccine that inhibits the hydrolytic shedding of MICA/B proteins from tumor cells, which induces tumor immunity via T and NK cells while avoiding the induction of antibodies that may block NKG2D receptor binding." (PMID 38380323, 2024). "Additionally, increased HIF-1α expression by tumor cells can decrease NK cell-mediated killing by downregulating tumor-derived MHC class I chain-related genes or by promoting the shedding of MICA, a ligand that triggers the cytolytic action of immune effectors, from the surface of tumor cells." (PMID 36980629, 2023). "The tumor escape from immune surveillance by the γδ T cells in these patients could therefore be due to the immunosuppressive profile of these cells plus an increase of soluble MICA derived from its shedding at the surface of lymphoma cells." (PMID 37426670, 2023). "Cleavage of NK activating ligands B7-H6 and MICA/B expressed on tumour cells and the subsequent release of these soluble ligands is a strategy through which tumour cells evade NK cell-mediated immune surveillance and thus may dampen the effects of NK cell therapies." (PMID 35364779, 2023). "Hence, MICA overexpression may be a valid strategy to limit tumour progression, as tumours exhibit escape strategies that subvert the biological functions of NKG2D." (PMID 37784183, 2023).
tumor (continued). "Interestingly, in T-and B cell leukemia/lymphoma, tumor cell increases MICA/B-containing exosome (or just small extracellular vesicles) secretion under oxidative stress, thereby preventing NKG2D from binding to the corresponding ligand on target cells by providing a decoy to bind NKG2D." (PMID 35692747, 2022). "Therefore, blocking ADAM17-mediated hydrolytic activity to inhibit MICA shedding may be one of the ways to improve NK cell killing of tumor cells." (PMID 36466812, 2022). "Therefore, the NKG2D-receptor and MicA may be considered responsible for the interaction of these lymphocytes with MHC-negative tumor cells." (PMID 34206968, 2021). "Currently, we cannot anticipate if Ab-based therapies against MICA/B may trigger antigen down-modulation on tumor cells and/or the selection of resistant tumor cells that lost expression of NKG2DL because of a selective killing of tumor cells that express the target molecule." (PMID 34394116, 2021). "However, tumor cells can successfully evade detection by NK cells by shedding MICA/B." (PMID 33440654, 2021). "Since tumor cells can regulate recognition signals and functionally modulate the expression of ligands for receptors on NK cells to mediate NK cell activity, we further investigated the dissimilarity in the expression of HLA-E and MICA/B in TNBC, RT-R-TNBC, and CD24−/low/CD44+ cells." (PMID 34502547, 2021). "Thus, MICAB1 efficiently promotes the ADCC and ADCP of MICA-expressing tumor target cellsin vitro." (PMID 35967081, 2021). "However, a limitation of the model could be the relatively harsh digestion procedure, which could affect tumor cell viability as well as surface expression of activating ligands MICA and MICB, leading to underestimation of the contribution of these ligands." (PMID 34203549, 2021). "Also, to increase the cytotoxicity of NK cells against tumor cells, a narrow-spectrum histone deacetylase inhibitor called Entinostat was used, which increased MICA expression on tumor cells and NKG2D expression in primary NK cells, even in the hypoxic environment." (PMID 34923966, 2021). "Also, MICA exhibits a very low tumor mutational burden, suggesting that its expression is not subject to DNA editing to confer some kind of adaptive advantage to tumors." (PMID 34394116, 2021). "Moreover, STAT3 signaling was proved to inhibit the expression of activation receptor NKD2G on NKs and its corresponding ligands MICA/B on tumor cells, which could block the activation of NKs and result in failing immune surveillance in HCC." (PMID 34566989, 2021). "In addition, Vδ1TCR could recognize tumor cells through MICA, but the MICA bindings by Vδ1TCR and NKG2D were mutually exclusive." (PMID 33664732, 2020). "Therefore, macrophages, like tumor cells, proteolytically shed MICA and MICB." (PMID 33424862, 2020). "Impairment of nitric oxide (NO) signaling is also associated with MICA/B shedding, and the accumulation of hypoxia-inducible factor-1α (HIF-1α) contributes to the immune escape by increasing ADAM10 expression to decrease surface MIC molecules on the tumor cell." (PMID 31396523, 2019). "In addition to the heterozygosity of MICA and the possible mechanism of proteolytic cleavage, the origin of tumor cells might also play an important role in the response to VPA." (PMID 30972064, 2019). "Therefore, antibodies specific for the α1 and α2 domains may have limited anti-tumor activity in the presence of soluble MICA." (PMID 31387641, 2019). "Moreover, IFN-γ promotes cytotoxic lymphocyte lysis via MICA regulation in tumor cells." (PMID 30013574, 2018).
tumor (continued). "Furthermore, MICA protein acts as a signal during the early immune response against infection and a lower level of this protein is thought to decrease the ability to alert the immune system of HPV infection, thus increasing the risk of tumour development." (PMID 28505207, 2017). "Therefore, our observation may be especially important, as treatments that upregulate MICA expression in spheroids may upregulate MICA expression in vivo where tumor MICA expression is often negligible." (PMID 28154561, 2016). "Additionally, 5-FU could increase MICA expression on HepG-2 or A549 cells and prevent membrane MICA from shedding as soluble MICA, which were abrogated in the tumor cells transfected with ADAM 10 overexpression plasmid." (PMID 27385218, 2016). "Moreover, the MICA-129 dimorphism might be relevant when considering therapies aiming at upregulation of MICA on tumor cells to sensitize them for NK cells." (PMID 28018354, 2016). "Ex vivo heating of tumor cells at 39.5 °C for 6 h could be used to increase the surface expressions of MHC class I-related chain A (MICA) which is a natural killer group 2D (NKG2D) ligand, thus making tumor cells more sensitive to cytolysis by natural killer [NK] cells." (PMID 26343191, 2015). "These include intrinsic defects of tumor cells such impaired expression of the HLA class I related antigen processing machinery and functional alterations of the tumor microenvironment (TM) induced by NB cell-derived immunosuppressive molecules as MICA and HLA-G." (PMID 23805414, 2013). "However, it has been unclear whether sorafenib reverses tumor escape mechanisms from host immunity after recognition of MICA expression." (PMID 22666283, 2012). "However, the surface expression of MICA/B was significantly down-regulated in A2780 cell line at the same time point, and this down-regulation could be dose dependent on γδ T cell: tumor cell ratio." (PMID 21935360, 2011). "Consequently, NKG2D/MICA interaction may represent an important activation pathway to trigger the immune attack against tumor cells." (PMID 18208618, 2008). "Tumors evade γδT cell-mediated cytotoxicity through several mechanisms, including the downregulation of NKG2D ligands (e.g., MICA, MICB, ULBPs), which are crucial for γδT cells to efficiently recognize and attack tumor cells." (PMID 40226616, 2025). "Tumor cell-platelet interactions also trigger the release of MICA and MICB from the tumor cell membrane into the TME." (PMID 39934930, 2025). "S-palmitoylation enhances the clustering of NK receptors such as NKG2D and 2B4 with their ligands (MICA/MICB) within cholesterol-rich microdomains, optimizing NK cell activation and tumor cell recognition." (PMID 40335986, 2025). "Multiple metalloproteinases hydrolyze MICA and MICB and convert them into soluble ligand molecules that inhibit NKG2D signal activation and impede the killing of tumor cells by NK cells and CD8+ T cells." (PMID 40563539, 2025). "Despite tumor hypoxia, entinostat increases NKG2D in NK cells and MICA in tumor cells, improving recognition and killing." (PMID 40510336, 2025). "As important ligand molecules of the NK cell-activating receptor NKG2D, MICA and MICB on the surface of tumor cells activate the anti-tumor effect of NK cells after binding to NKG2D." (PMID 40563539, 2025). "For example, the NKG2D-IL-15 fusion protein needs to bind to MICA on the surface of tumor cells, and this binding hinders the binding of NKG2D on NK cells to MICA on tumor cells, which is unfavorable for the activation of NK cells." (PMID 40563539, 2025). "The ability of 23ME-01473 to activate NK cells and induce tumor growth control in vivo was evaluated using a humanized NSCLC PDX model that endogenously expresses cell surface ULBP6/2/5 and MICA/B and produces sULBP6/2/5." (PMID 40116579, 2025).
tumor (continued). "Palmitoylation facilitates the surface expression of MICA and augments their interaction with the NK cell receptor NKG2D, therefore amplifying NK cell activation and tumor cell cytotoxicity." (PMID 40066091, 2025). "MICA and MICB on the surface of tumor cell membranes can bind to the NKG2D receptor on the surface of NK cells, activating NK cells to perform cytotoxic effects." (PMID 40563539, 2025). "We next assessed the NSCLC tumor biopsy from patient 006 for expression of the cognate ligands for NKGD2 (i.e., MICA/B), DNAM-1 (i.e., CD112), and NKp30 (i.e., B7H6 and BAG6)." (PMID 39903538, 2025). "The COAD tumor samples showed an increase between 4.5 and 11.3-fold for ULBP1/2/3/6 compared to normal tissues, and MICA and MICB had expression increases of 1.29 and 1.89-fold." (PMID 40013140, 2025). "These subpopulations exhibited differential expression of surface tumor antigens, including the CAR target (i.e., CD33), the NKT TCR target (i.e., CD1d), and NKR ligands (i.e., CD112, CD155, and MICA/B)." (PMID 39893165, 2025). "When NKG2D binds to stress-induced cellular ligands on tumor cells, like MHC class I chain-related proteins A/B (MICA/B), it can also induce NK cell cytotoxicity." (PMID 41181137, 2025). "Monoclonal antibodies against MICA and MICB can enhance the activation of NK cells and γδT cells, leading to the cytotoxicity of the tumor cells." (PMID 40226616, 2025). "Stress-induced ligands such as MICA and ULBP on tumor cells are recognized by NKG2D on T-IELs, initiating FasL-mediated cytotoxicity and direct tumor killing." (PMID 40005486, 2025). "In contrast, ATC tumor cells upregulate stress ligands, such as UL16-binding proteins (ULBPs) and MHC class I polypeptide-related sequence A/B (MICA/B), which are ligands for NKG2D on NK cells, suggesting susceptibility to NK-mediated killing." (PMID 40710340, 2025). "The high expression of MICA and MICB on the surface of various epithelial cell-derived malignant tumors makes them potential therapeutic targets and important mediators of tumor immune escape." (PMID 40563539, 2025). "Second, γδ T cells can identify MICA/B expressed on M2 TAMs via NKG2D, enabling direct cytotoxicity and disruption of the tumor-promoting milieu." (PMID 41488642, 2025). "Activation of the NKG2D/MICA signaling axis subsequently enhances NK cells expression of perforin, granzyme B, and NKG2D, improving their ability to kill tumor cells." (PMID 40557764, 2025). "The purpose of tumor cells expressing MICA or MICB is to activate NK cells, γδT cells, or CD8+T cells to kill tumor cells and promote anti-tumor immunity." (PMID 40563539, 2025). "Activating receptors, including NKG2D, NKp30, and NKp46, recognize stress-induced ligands (e.g., MICA, MICB) or tumor-specific proteins upregulated on the tumor cell surface." (PMID 40236691, 2025). "When examining the effect of CuET on NKG2DLs expressed in human tumor cell lines (HCT116 and HT-29), we observed effective upregulation of MICA/B and ULBP1/2 at the mRNA and protein levels." (PMID 40013140, 2025). "ULBP2, like MICA and MICB, is a human NKG2D ligand, and its ectopic expression in murine tumor cells carries the potential for immune rejection due to its xenogeneic nature." (PMID 40243581, 2025). "Abnormal expression of metalloproteinases is regulated by HIF-1α, which induces the expression of MMP2, MMP9, ADAM10, etc., in tumor cells, hydrolyzing MICA and MICB on the surface of tumor cells and mediating immune escape." (PMID 40563539, 2025). "Elevated MMP9 activity in HCC drives the proteolytic cleavage of MHC class I chain-related protein A (MICA), leading to the release of soluble MICA and enabling tumor immune evasion." (PMID 40283942, 2025). "This pivotal immunoreceptor recognizes eight distinct ligands (MICA, MICB, and ULBP/RAET1 family members), orchestrating immune recognition through direct tumor cell engagement." (PMID 40726981, 2025).
tumor (continued). "In order to explore the killing ability of IL15C-CAR T on tumor cells, PANC-1 and PANC-28 which highly express MICA/B were used as target cells, and SW1990 which express low level of MICA/B was used as a negative control." (PMID 40625735, 2025). "Enhances tumor immunogenicity by increasing immune ligands (MHC I, MICA/B, ULBP2/5/6) on cancer cells, promotes cytotoxic T cell and NK cell activation; supports immune clearance of tumors." (PMID 39949780, 2025). "We observed a significant downregulation of NKG2D ligands, such as MICA, MICB and ULPB1, 2, and 3 following BET/JQ1treatment of the human tumor cells with similar findings noted in mouse N2a treated cells as well (Ulbp1, Rae1a and Rae1b)." (PMID 40552293, 2025). "The MICA and MIC-B are membrane-bound molecules present on the surface of the tumor cells, where they bind to the natural killer group 2D (NKG2D) on NKs." (PMID 40108523, 2025). "Previous studies have also evaluated the immunological effects of human NKG2D ligands, such as MICA and MICB, by expressing them in murine tumor models." (PMID 40558520, 2025). "The regulation of MICA and MICB by HIF-1α and metalloproteinases is of great significance for understanding tumor progression and molecular targeting." (PMID 40563539, 2025). "One of the most well-characterized NKRs expressed on γδT cells is NKG2D, which binds to MICA, MICB, and ULBPs, stress-induced ligands commonly upregulated in tumor cells." (PMID 40226616, 2025). "Alternatively, platelet coating reduced surface expression of NKG2D ligands, in particular, MHC class I chain-related sequence A (MICA) and MICB, on tumor cells and thereby diminished NKG2D-dependent lysis of tumor cells." (PMID 40427186, 2025). "This molecule comprises a MICA extracellular domain (MICA-ECD) for NKG2D binding, an anti-CD20 single-chain variable fragment (ScFv) for CD20 recognition on tumor cells, and a human IgG Fc fragment." (PMID 39007146, 2024). "Vorinostat downregulated microRNA-20a, diminished STAT3 tyrosine phosphorylation, and increased histone acetylation at MICA and MICB promoters, leading to increased expression of these genes and enhanced natural killer (NK) cell-mediated tumor targeting." (PMID 38915093, 2024). "We confirmed that persistent exposure to excessive soluble MICA leads to the internalization of NKG2D and subsequent lysosomal degradation, impairing the function of NK cells and promoting tumor immune escape." (PMID 39048814, 2024). "We examined the surface expression of MICA/B, ULBP1, ULBP2/5/6 and ULBP3 on SKOV-3, BT-474 and MCF-7 tumor cells growing in 3D culture after spheroid dissociation." (PMID 39457710, 2024). "Consistent with our previous research, we observed a significant upregulation of PROS1 in MICA+ and IRF1+ tumor cells." (PMID 38254761, 2024). "This increase in MICA expression enhances the ability of NK and CD8+ T cells to identify and attack SNU719 cells, making the tumor cells more vulnerable to immune-mediated cytotoxicity." (PMID 39335190, 2024). "NKG2D in Vδ2 T cells binds to MHC class I polypeptide-related sequence A/B (MICA/B), retinoic acid early inducible 1 (Rae-1) and UL16 binding proteins (ULBP) found on tumor cells." (PMID 39748921, 2024). "Previous studies have described that Vδ1 γδ T cells recognized stress-induced antigens, such as MHC class I-related chain A (MICA and MICB), expressed on epithelial tumor cells through the ligand, natural killer group member 2-D (NKG2D)." (PMID 38915409, 2024). "In this study, we presented a single-cell atlas of advanced HCC, revealing distinct expression patterns of MICA and MMP9 in tumor cells and macrophages, respectively." (PMID 38254761, 2024). "NKG2D plays an important role in the anti-tumor activity of NK cells due to its ability to bind to MHC-I-chain-related molecules, such as MICA, MICB, and the UL16-binding proteins (ULBPs)." (PMID 39339180, 2024).